ENSG00000212377
Synonyms: LOC124900345
Gene: Small nucleolar RNA gene on chromosome 13 (72,453,902 to 72,453,967, reverse strand). Ensembl gene ENSG00000212377.
Gene Ontology:
Biological process: RNA processing
Cellular component: nucleolus
Homologues: Paralogues in human: SNORD37 (73% identical).